FGFR2 (fibroblast growth factor receptor 2)
Diseases named in the same sentence as FGFR2 in open-access papers (continued):
Sharing a sentence is not in itself a finding about the gene and the disease.
cholangiocarcinoma (continued). "As compared with the other member of the FGFR family, FGFR2 had several reported partners and FGFR2 fusions are particularly common in cholangiocarcinoma." (PMID 32962091, 2020). "In this regard, a study evaluated the presence of FGFR2 translocations in 152 cholangiocarcinoma and 4 intraductal papillary neoplasms of the bile duct by FISH." (PMID 32962091, 2020). "A phase III study comparing infigratinib and chemotherapy (cisplatin and gemcitabine) in FGFR2 fusion cholangiocarcinoma in the first-line setting is currently underway (NCT03773302)." (PMID 35582593, 2019). "In a phase I dose expansion cohort of FGFR2 translocated cholangiocarcinoma receiving erdafinitib (n = 11), objective responses were observed in 3 patients (27.3%) with an additional 3 patients achieving stable disease." (PMID 35582593, 2019). "Through rapid research autopsy and WES, we determine the presence of four tumor subclones and elucidate their evolution in metastatic tissues over time in a patient with FGFR2-fusion-positive cholangiocarcinoma." (PMID 31371345, 2019). "In a phase I/II open label study in patients with FGFR2 fusion cholangiocarcinoma (n = 29), the ORR was 20.7% and disease control rate (DCR) was 82.8%." (PMID 35582593, 2019). "For example, the results of a phase II trial (NCT02150967) showed meaningful clinical activity of BGJ398 against advanced/metastatic and chemotherapy-refractory cholangiocarcinoma with FGFR2 fusions who progressed with first-line chemotherapy." (PMID 30326595, 2018). "ARQ 087 is currently being studied in a phase 1/2 clinical trial that includes a sub cohort for intrahepatic cholangiocarcinoma patients with confirmed FGFR2 gene fusions (NCT01752920)." (PMID 27627808, 2016). "A large number of FGFR2 gene fusions have been identified in cholangiocarcinoma, and FGFR inhibitors have shown to be partially effective in reducing tumor burden in patients." (PMID 27627808, 2016). "A clinical response was noted for a patient with intrahepatic cholangiocarcinoma with a known FGFR2 fusion, additionally prolonged stable disease was observed in 10 of 61 patients, including a cholangiocarcinoma, which also had an FGFR2 fusion." (PMID 27627808, 2016). "Tumor reductions were also observed in cholangiocarcinoma with an FGFR2 gene fusion, and FGFR1-amplified breast cancer." (PMID 27409839, 2016). "Recently, two independent studies reported the presence of FGFR fusions in cholangiocarcinoma; a single case with FGFR2-AHCYL1 as well as several cases identifying FGFR2-BICC1 fusions." (PMID 24550739, 2014). "Larger trials, preferably of a randomized nature with a control arm, need to be conducted to truly define the role of FGFR inhibitors in the treatment of patients with cholangiocarcinoma, particularly those harboring FGFR2 fusions." (PMID 24550739, 2014). "This Phase 2 study found that tasurgratinib 140 mg daily had promising antitumor activity, safety, and tolerability in patients with cholangiocarcinoma harboring fibroblast growth factor receptor 2 fusions/rearrangements after ≥1 prior gemcitabine-based chemotherapy regimen." (PMID 40795150, 2025). "Infigratinib and pemigatinib are approved for cholangiocarcinoma with an FGFR2 rearrangement." (PMID 41323387, 2025). "While molecular targeted therapies against FGFR2 fusion have been proved to be useful in cholangiocarcinoma, the therapeutic significance of FGFR2 inhibitors remains unclear in other various solid cancers." (PMID 41226813, 2025). "For instance, in patients diagnosed with FGFR2 fusion- or rearrangement-positive cholangiocarcinoma, significant improvements in patient outcomes were observed in treatment with futibatinib, a covalently binding inhibitor of FGFRs, and infigratinib, a selective, ATP-competitive inhibitor of FGFRs." (PMID 40393028, 2025).
cholangiocarcinoma (continued). "In cholangiocarcinoma, NTRK1-3 fusions are estimated to occur in about 3.6% of cases, particularly intrahepatic subtypes, and represent one of the few actionable alterations beyond FGFR2 fusions and IDH1 mutations." (PMID 41153346, 2025). "One of the reasons might be that FGFR2 abnormalities were frequent in cholangiocarcinoma and gastric cancers, which were relatively frequent in younger age." (PMID 41226813, 2025). "The ongoing FIGHT-302 study (Phase III, randomized controlled trial; pemigatinib vs. gemcitabine + cisplatin, 2:1 randomization; primary endpoint: PFS) is designed to evaluate the efficacy and safety of pemigatinib as first-line therapy for advanced FGFR2-rearranged cholangiocarcinoma." (PMID 41514604, 2025). "While rare in most cancers, these fusions indicate poor prognosis and are candidates for FDA-approved FGFR-targeted therapies, including infigratinib, pemigratinib and futibatinib for cholangiocarcinoma with FGFR2 fusions and erdaftinib for urothelial cancers with FGFR3 fusions." (PMID 40711866, 2025). "That study will investigate tinengotinib monotherapy in patients with cholangiocarcinoma with FGFR2 fusions for whom prior FGFR inhibitor therapy was unsuccessful, or those who responded to previous FGFR inhibitor(s), or with other FGFR alterations, or wild-type FGFR." (PMID 38297981, 2024). "Besides FGFR2 fusions, mutations and amplifications of FGFR1 and FGF3 and the overexpression of FGFR4 were also reported in subsets of cholangiocarcinoma cases." (PMID 39796710, 2024). "This phase II trial was a bridging study to assess whether the efficacy and safety findings for pemigatinib in FIGHT‐202 could be extrapolated to previously treated Chinese patients with cholangiocarcinoma carrying FGFR2 fusions or rearrangements." (PMID 36127767, 2023). "Similarly, pemigatinib appears to be beneficial in previously treated patients with cholangiocarcinoma with FGFR2 fusions or rearrangements." (PMID 37091141, 2023). "Interestingly, this is somewhat in contrast to our previous findings in cholangiocarcinoma with FGFR2 fusions, in which we found that quisinostat can upregulate the activation of FGFR and Erk signaling." (PMID 37479885, 2023). "Durations of treatment and follow‐up were relatively short as of the data cutoff, limiting time‐to‐event and safety assessments; the mature OS data will provide additional evidence for efficacy of pemigatinib in Chinese patients with cholangiocarcinoma and FGFR2 rearrangements." (PMID 36127767, 2023). "Twenty‐one centres participated in the external FGFR2 round robin test for cholangiocarcinoma." (PMID 36635225, 2023). "It is plausible that the downregulation of FGFR3 by quisinostat we observed in this study may be either an FGFR isoform specific (FGFR3 vs. FGFR2) or a cancer type specific (bladder cancer vs. cholangiocarcinoma) effect." (PMID 37479885, 2023). "Four patients with cholangiocarcinoma had SD, three of whom had FGFR2 alterations." (PMID 37000035, 2023). "E7090 selectively inhibits FGFR1–3 and has been found to be effective in patients with cholangiocarcinoma with FGFR2 gene fusions and in patients with gastric cancer with FGFR2 gene amplification or increased expression, but more information is needed for a larger sample size." (PMID 37750089, 2023). "In China, an NGS‐based companion diagnostic for pemigatinib (Malignant Neoplasms Multi‐Gene Analysis Kit) is being developed in parallel, to be used for identifying patients with cholangiocarcinoma carrying FGFR2 rearrangements who are eligible for pemigatinib treatment." (PMID 36127767, 2023). "In our pursuit to determine whether FGFR2 mutations could increase the therapeutic sensitivity of ICC cells, we employed human cholangiocarcinoma RBE cells as a model system and infected them with lentiviruses expressing a range of FGFR2 mutations." (PMID 37964396, 2023).
cholangiocarcinoma (continued). "Despite that these results suggest that infigratinib has activity in cholangiocarcinoma harboring FGFR2 fusions previously treated with systemic therapy, the discontinuation of the development of infigratinib precludes the implementation of the agent in first-line treatment." (PMID 37681152, 2023). "Furthermore FGFR2 fusions/rearrangements events have demonstrated their clinical relevance in cholangiocarcinoma patients, which benefit from treatment with selective FGFR1-3 inhibitors." (PMID 35246724, 2023). "In patients with cholangiocarcinoma carrying FGFR2 fusions or rearrangements, pemigatinib 13.5 mg once daily resulted in an objective response rate (ORR) of 35.5%, with a median duration of response (DOR) of 7.5 months, and a disease control rate (DCR) of 82.2%." (PMID 36127767, 2023). "In a study evaluating patient-derived models of FGFR2-fusion-positive cholangiocarcinoma, inhibition of EGFR potentiated responses to FGFR inhibitors, durably suppressing MEK/ERK and mTOR signaling, increasing apoptosis, and causing marked tumor regressions in vivo." (PMID 35444941, 2022). "FGFR2 fusion was studied more in-depth in advanced cholangiocarcinoma." (PMID 36292044, 2022). "Indeed, the promising results of pemigatinib and infigratinib were shown in advanced unresectable cholangiocarcinoma harboring FGFR2 fusions or rearrangements, and erdafitinib in metastatic urothelial carcinoma with FGFR2 and FGFR3 genetic aberrations." (PMID 35327403, 2022). "In addition, it is in phase III trial (NCT04093362) for advanced cholangiocarcinoma harboring FGFR2 gene rearrangements." (PMID 36254250, 2022). "Furthermore, based on the results of FOENIX trials, futibatinib was approved by FDA this year for the treatment of locally advanced or metastatic cholangiocarcinoma whose tumours harbor an FGFR2 rearrangement or fusion." (PMID 36497187, 2022). "In addition, FGFR2 fusions occur in cholangiocarcinoma, lung squamous cell carcinoma (LSCC), thyroid cancer, prostate cancer, according to a study of FGFR targetable gene fusions." (PMID 35494629, 2022). "However, in Japan, pemigatinib is the only drug approved for the treatment of unresectable cholangiocarcinoma patients with FGFR2 gene fusion." (PMID 35945547, 2022). "On April 17, 2020, the US Food and Drug Administration granted accelerated approval for PMB for the treatment of adults with previously treated, unresectable metastatic or locally advanced cholangiocarcinoma with a fibroblast growth factor receptor 2 (FGFR2) fusion or other rearrangement." (PMID 35919584, 2022). "On May 2021, based on these results, the FDA granted accelerated approval for infigratinib for the treatment of patients with previously treated advanced cholangiocarcinoma with an FGFR2-fusion or rearrangement." (PMID 35444941, 2022). "FGFRis of interest in cholangiocarcinoma with FGFR2 genomic alterations." (PMID 35444941, 2022). "On the contrary, the other cholangiocarcinoma samples such as PC47 possessed many of the top 20 genomic mutations such as NOTCH mutations but had no FGFR2 fusion." (PMID 36213130, 2022). "Based on the promising result, the Food and Drug Administration (FDA) granted accelerated approval to pemigatinib (PEMAZYRE, Incyte Corporation, Wilmington, DE, USA) for the treatment of patients with previously treated cholangiocarcinoma with FGFR2 fusion or other rearrangements in April 2020." (PMID 33451059, 2021). "Also, another FGFR inhibitor Pemigatinib was granted accelerated approval by the Food and Drug Administration for cholangiocarcinoma with an FGFR2 fusion or rearrangement in the United States25." (PMID 33692336, 2021). "Fibroblast growth factor receptor 2 (FGFR2) fusions have emerged as a new therapeutic target for cholangiocarcinoma in clinical practice following the United States Food and Drug Administration (FDA) approval of Pemigatinib in May 2020." (PMID 33800328, 2021).
cholangiocarcinoma (continued). "Several gatekeeper mutations in the FGFR family have been reported in preclinical studies in several cancer models, including FGFR1 V561M in lung cancer, FGFR2 V565I/N550K/V564F in endometrial cancer and cholangiocarcinoma, FGFR3 V555M in myeloma and FGFR4 V550L/V550E in rhabdomyosarcoma." (PMID 34068816, 2021). "Currently, infigratinib is in a phase III study (NCT03773302) as first-line treatment for patients with cholangiocarcinoma harboring FGFR2 gene translocations, and in a phase I study (NCT04424966) in patients with high-grade glioma carrying FGFR3–TACC3 fusions." (PMID 34732230, 2021). "According to the latest 2020 National Comprehensive Cancer Network (NCCN) guidelines (United States), if FGFR2 gene fusion or rearrangement is clinically detected in cholangiocarcinoma, the targeted drug pemigatinib can be used for treatment, and there is a favorable response." (PMID 33935756, 2021). "Fusions containing FGFR2 are most common in cholangiocarcinoma." (PMID 34068954, 2021). "For example, BGJ398 has been granted Fast Track Designation by FDA for treating cholangiocarcinoma with FGFR2 gene fusions due to the phase II study (NCT02150967) with an encouraging progression-free survival (PFS, 5.8 months), response rate (14.8%), and disease control rate (75.4%)." (PMID 33568192, 2021). "We found three cases carrying fusions with FGFR2, which might predict response to ponatinib as previously shown in cholangiocellular carcinoma." (PMID 33441414, 2021). "The promising results of pemigatinib and infigratinib in advanced unresectable cholangiocarcinoma harboring FGFR2 fusions or rearrangement, and erdafitinib in metastatic urothelial carcinoma with FGFR2 and FGFR3 genetic aberrations, lead to their accelerated approval by the United States (USA) FDA." (PMID 34199304, 2021). "In addition to non-selective tyrosine kinase inhibitors, which have shown activity in cholangiocarcinoma with FGFR2 fusion, a number of phase II trials have demonstrated efficacy for targeted FGFR inhibitors." (PMID 34439216, 2021). "Gene fusions involving FGFR2 occur in 7%-14% of intrahepatic cholangiocarcinomas." (PMID 35582593, 2019). "CNV-genes FGFR2 could induce cholangiocarcinoma cell migration via activation of the MEK1/2 pathway." (PMID 24897108, 2014). "Thus, we believe that biparatopic antibodies may serve as an innovative treatment option for patients with FGFR2-altered cholangiocarcinoma." (PMID 40014401, 2025). "Furthermore, the therapeutic significance of FGFR2 abnormalities for these cancers, except cholangiocarcinoma, remains unclear." (PMID 41226813, 2025). "In particular, pemigatinib and futibatinib were approved for the treatment of unresectable, previously treated, locally advanced, or metastatic cholangiocarcinoma (CCA) with FGFR2 fusion." (PMID 41154409, 2025). "Fibroblast growth factor receptor 2 (FGFR2) fusions and rearrangements are clinically actionable genomic alterations in cholangiocarcinoma (CCA)." (PMID 38838500, 2024). "Notably, both FGFR2 fusions and IDH1 mutations are rare in fluke-associated cholangiocarcinomas." (PMID 37891989, 2023). "FGFR2 fusions occur almost exclusively in iCCA, with a frequency of 10%–15%, and are rare in extrahepatic cholangiocarcinoma (CCA) and other epithelial cancers." (PMID 37493315, 2023). "For cholangiocarcinomas in particular, molecular techniques can evaluate the possibility to target actionable genomic alterations with approved agents such as include ivosidenib for tumors harboring IDH1 mutations, and infigratinib and pemigatinib for those with FGFR2 fusions." (PMID 37091141, 2023). "FDA has approved several targeted therapies for cholangiocarcinoma (CCA), including drugs that target IDH1 mutation and fibroblast growth factor receptor 2 (FGFR2) fusions in genetically selected populations." (PMID 37814942, 2023).
cholangiocarcinoma (continued). "Therefore, at the time of writing, the sponsor intends to halt the ongoing phase III PROOF-301 (NCT03773302), in which infigratinib is evaluated as a potential first-line treatment in advanced or inoperable cholangiocarcinoma harboring FGFR2 gene fusions or translocations." (PMID 37681152, 2023). "Furthermore, futibatinib has demonstrated clinical efficacy in patients harboring FGFR2-fusion-driven cholangiocarcinoma, and is in clinical trials to assess its efficacy in the treatment of solid or myeloid and lymphoid neoplasms with FGFR1 re-arrangements (NCT04189445)." (PMID 35574218, 2022). "For instance, results of contemporary clinical trials investigating FGFR2 inhibition in cholangiocarcinoma, including infigratinib (NCT03773302) and futibatinib (NCT04093362), could perhaps be extrapolated to patients with FGFR2 fusion positive, KRAS wildtype PDAC." (PMID 36209277, 2022). "Notably, FGFR2 fusions are also present in 13–17% of intrahepatic cholangiocarcinomas." (PMID 32411236, 2020). "We note that only four SNVs, three indels, and one copy-number gain were detected in the trunk of this patient's phylogenetic tree (branch a), indicating that development of FGFR2-fusion-positive cholangiocarcinoma may only require a small number of other initiating events." (PMID 31371345, 2019). "In April 2022, the US Food and Drug Administration (FDA) granted accelerated approval of this TKI for previously treated patients with advanced or metastatic cholangiocarcinoma (CCA) harboring FGFR2) fusions and other rearrangements based on results from the phase II FIGHT-202 trial (NCT02924376)." (PMID 41154409, 2025). "Our findings establish FGFR2::SHTN1 as a potent oncogenic driver in various cancers, particularly in cholangiocarcinoma, highlighting a unique mechanism of constitutive activation mediated by Shootin1’s CCD-II domain." (PMID 41496852, 2025). "Consistent with results in FGFR2 fusion–expressing NIH3T3 cells, treatment of the ICC13-7 cholangiocarcinoma cell line with bpAb-B/C and bpAb-B/D led to increases in fluorescent signals compared with parental antibodies." (PMID 40014401, 2025). "Increased RAD51 foci have been documented in FGFR2 driven cholangiocarcinoma cells exposed to ionising radiation, and similar findings were reported in an imatinib-resistant GIST patient-derived xenograft harbouring FGFR2 TACC2." (PMID 41150770, 2025). "For instance, pemigatinib has received approval for the management of advanced cholangiocarcinoma because of its potent activity as a selective oral small-molecule inhibitor of FGFR1, FGFR2, and FGFR3." (PMID 40898491, 2025). "In addition to patients with cholangiocarcinoma, we saw polyclonal acquired resistance in patients with FGFR2-altered gastroesophageal/gastroesophageal junction cancer and cancer of unknown primary origin, FGFR3-altered non-small cell lung cancer and FGFR1-altered pancreatic cancer." (PMID 38710951, 2024). "BRAF, erb-b2 receptor tyrosine kinase 2 (ERBB2), fibroblast growth factor receptor 2 (FGFR2), and isocitrate dehydrogenase 1 (IDH1) genes have been reported as therapeutically relevant genomic alterations in cholangiocarcinoma patients." (PMID 37108676, 2023). "Four patients with cholangiocarcinoma had SD; of whom one had a centrally confirmed FGF1 and FGFR2 amplification and one had a centrally confirmed FGFR2 rearrangement and locally identified FGFR2 translocation." (PMID 37000035, 2023). "FGFRs are aberrantly activated in cholangiocarcinoma (CCA) and most of the alterations involve the FGFR2 coding gene." (PMID 37715207, 2023). "Pemigatinib is the first approved drug for treating severe cholangiocarcinoma as an inhibitor of FGFR1, FGFR2, and FGFR3 receptors." (PMID 35911272, 2022). "To date, the FDA has approved erdafitinib for urothelial cancer with FGFR2 or FGFR3 alterations, as well as pemigatinib and infigratinib for cholangiocarcinoma with FGFR2 fusions or other rearrangements." (PMID 36455506, 2022).